CYP7A1 (cytochrome P450 family 7 subfamily A member 1)
Diseases named in the same sentence as CYP7A1 in open-access papers (continued):
Sharing a sentence is not in itself a finding about the gene and the disease.
acute myocardial infarction (2 papers, 2021 to 2025). Necrosis of the myocardium, as a result of interruption of the blood supply to the area. "For example, polymorphisms in the CYP7A1 (cytochrome P450 family 7 subfamily A member 1) gene encoding the enzyme mediating the rate-limiting step in bile acid synthesis are associated with increased levels of LDL-C and increased risk of myocardial infarction." (PMID 35011746, 2021).
Alcohol (2 papers, 2022 to 2025).
hepatic disorder (2 papers, 2021 to 2022). "Conversely, regarding FGF19 activity and its analogs in the liver, we do not have enough data to understand how these compounds suppress Cyp7a1 and genes that facilitate hepatic disorder development." (PMID 35682726, 2022). "Studies so far have attributed the hepatoprotective effects of intestine-derived FGF15 largely to the activation of gut-liver signaling feedback inhibition of CYP7A1, and the activation of FGF15 has been thought to provide promise for improving liver disease pathogenesis." (PMID 34736501, 2021).
hyperthyroidism (2 papers, 2014 to 2016). Overactivity of the thyroid gland resulting in overproduction of thyroid hormone and increased metabolic rate. "In the present study, serum levels of C4, a metabolite formed in the classical bile acid synthetic pathway that closely reflects CYP7A1 activity and bile acid synthesis, were 43% higher in hyperthyroidism, showing that bile acid synthesis is stimulated by TH in humans." (PMID 25172631, 2014).
hyperuricemia (2 papers, 2022 to 2023). An abnormally high level of uric acid. "We found that the relative mRNA levels of hepatic FGF21 was lower by 31% in the hyperuricemia mice than that in the control, demonstrating that the over-expression of CYP7A1 in the liver was linked to a glucocorticoid disorder." (PMID 38034015, 2023). "In the liver of the hyperuricemia mice, CYP7A1 expression was significantly higher than the control by 441%." (PMID 38034015, 2023). "The high uric acid level did not affect the expression of cholesterol synthesis enzyme 3-hydroxy-3-methylglutaryl-CoA reductase (HMGCR), but reduced expression of CYP7A1 by 70.2% in the liver of hyperuricemia mice." (PMID 35565954, 2022).
Hypocholesterolemia (2 papers, 2014 to 2017). An decreased concentration of cholesterol in the blood. "It is well known that an increase in CYP7A1 mRNA induces hypocholesterolemia due to overexpression of CYP7A1 and this effect can be induced by dietary treatment such as soybean peptide feeding, causing an increase in fecal steroids excretion, similar to our present results in animal studies." (PMID 25144734, 2014).
Sepsis (2 papers, 2021 to 2023). Sepsis is defined as life-threatening organ dysfunction caused by a dysregulated host response to infection. "Among that, Lrp5, Cyp7a1, Nfkbiz, Sigmar1, Fabp7, and Hao1 have been reported in the inflammatory response and lipid metabolic process, suggesting that these genes may play an important role in modulating sepsis-induced system inflammation in WT and LBP-deficient rats after LPS injection." (PMID 35005033, 2021). "Moreover, we corroborated the results of the repressed liver metabolic processes and enhanced the immune response in sepsis mice via RT-qPCR targeting the marker genes, such as Acaca, Acacb, Cyp7a1, FGF2, and A2m." (PMID 37512913, 2023).
alcoholic hepatitis (1 paper, 2021). Acute hepatitis resulting from ingestion of alcohol. "In contrast, hepatic Cyp7a1 was slightly, but not significantly, increased in gnotobiotic mice colonized with stool from alcoholic hepatitis patients, which is more similar to patients with alcohol-related steatohepatitis and alcoholic hepatitis." (PMID 34198609, 2021).
alcoholic liver diseases (1 paper, 2019). A disorder caused by damage to the liver parenchyma due to alcohol consumption. "Another research revealed that CYP7A1 and its related cholesterol process were adversely regulated between non-alcoholic fatty liver disease and alcoholic liver disease, so it's possible that the increasing CYP7A1 levels in liver tissue are the consequence rather than cause of NAFLD." (PMID 31551930, 2019).
biliary atresia (1 paper, 2022). A rare, biliary tract disease characterized by progressive obliterative cholangiopathy of the intra- and extrahepatic bile ducts, occurring in the embryonic/ perinatal period, leading to severe and persistent neonatal jaundice and acholic stool. "Bioinformatics analysis showed that the expression of PPARα, CYP7A1 and NR1H4 (FXR) in the biliary atresia group was significantly lower than in the control group." (PMID 36090996, 2022).
chronic renal failure (1 paper, 2019). "Several studies have reported that hepatic CYP7A1 activity is virtually identical in chronic renal failure (CRF) rats and healthy controls, and BAs production rate is intact as well." (PMID 31637223, 2019).
Co-infection (1 paper, 2013). "Co-infection with lentivirus expressing RNAi-resistant Prox1 mutant (lenti-Prox1m) reinstated Prox1 expression (top, lanes 5–6), and intracellular CYP7A1 mRNA level also returned to a level comparable to HepG2 cells infected with control lentiviruses (bottom, bars 5–6)." (PMID 23626788, 2013).
extrahepatic cholestasis (1 paper, 2016). Impairment of the bile flow caused by an obstruction in the portion of the bile duct system located outside of the liver. "Experimentally stimulated intestinal Fxr transcription reduced the hepatic BA pool in mice with intrahepatic or extrahepatic cholestasis, in association with Fgf15 synthesis activation, leading to suppression of Cyp7a1 and Cyp8b116." (PMID 28008998, 2016).
HCMV infection (1 paper, 2018). "After HCMV infection of Hep cells, activity of the CYP7A1 promoter and the activity of G2 are significantly decreased, and the infection interferes with cholesterol metabolism by affecting the activity of the hepatic CYP7A1 promoter." (PMID 29409508, 2018).
hepatitis B virus infection (1 paper, 2022). A viral infection caused by the hepatitis B virus. "Factors affecting the activity of CYP7A1 also include genetic polymorphism in the CYP7A1 gene, hepatitis B virus infection (virus binding to the cellular receptor leads to decreased CYP7A1 expression), and vitamin C content (necessary for the regeneration of iron in the cytochrome)." (PMID 35335345, 2022).
hyperandrogenemia (1 paper, 2026). "Concurrently, hyperandrogenemia reduces the bile acids pool by downregulating hepatic bile acids synthesis enzymes, including CYP7A1." (PMID 41514462, 2026).
intestinal schistosomiasis (1 paper, 2020). An intestinal infection that is caused by Schistosoma japonicum. "The activity of the cytochrome P450 family of enzymes, which include CYP2E1 and CYP7A1, has been reported to be modulated by intestinal schistosomiasis, contingent on granulomatous reactions around the eggs in the tissue." (PMID 32111243, 2020).
intestinal tumor (1 paper, 2018). "Collectively, the current study, as the demonstration for utility of the model, identifies cyp7a1 as a host gene that mediates liver inflammation, one of the adverse effects on the host caused by the intestinal tumor." (PMID 29592890, 2018). "Intriguingly, cyp7a1 overexpression in the liver was associated specifically with buffered liver inflammation: the number of neutrophils in the liver was increased in the presence of the intestinal tumor, which was significantly ameliorated by overexpression of cyp7a1 in the liver." (PMID 29592890, 2018). "Notably, we found that hepatic cyp7a1, the gene encoding the rate-limiting enzyme that acts at the first step of converting cholesterol to bile acids, in the case of zebrafish, BA, tended to be reduced in the presence of the intestinal tumor." (PMID 29592890, 2018). "Yet, studies in different contexts support our observation that the intestinal tumor actively reduces expression of hepatic cyp7a1 to promote liver inflammation." (PMID 29592890, 2018). "Here, we establish a novel zebrafish intestinal tumor model that is suitable for addressing this issue, and find that hepatic cyp7a1, the rate-limiting factor for synthesizing bile acids [or, in the case of zebrafish, bile alcohol (BA)], is such a host gene." (PMID 29592890, 2018). "Does cyp7a1-mediated liver inflammation benefit the intestinal tumor?" (PMID 29592890, 2018). "Thus, we found a previously unknown role of cyp7a1 as the host gene that links the intestinal tumor, hepatic cholesterol–BA metabolism and liver inflammation in tumor-bearing zebrafish larvae." (PMID 29592890, 2018).
Iron deficiency (1 paper, 2020). "Iron deficiency increased the hepatic mRNA expression of cyp7a1, OTC, and AS (p < 0.05)." (PMID 32764239, 2020).
iron overload (1 paper, 2024). "In conclusion, FA can protect the liver from lipid and bile acid metabolism disorders caused by iron overload by targeting FASN and CYP7A1." (PMID 39594419, 2024).
ischemia (1 paper, 2025). A hypoperfusion of the BLOOD through an organ or tissue caused by a PATHOLOGIC CONSTRICTION or obstruction of its BLOOD VESSELS, or an absence of BLOOD CIRCULATION. "CYP7A1 deficiency may reduce cholesterol catabolism, synergizing with lipid-driven ischemia." (PMID 41211142, 2025).
ischemic stroke (1 paper, 2025). A stroke disorder caused by obstruction of blood flow to the brain, due to thrombotic (local blood clot formation) or embolic (due to a blood clot or other material traveling from another site) event. "A clinical trial involving 121 patients with ischemic stroke reports associations between nucleotide polymorphisms in CYP11B2, CYP2E1, and CYP7A1 and the occurrence of ischemic stroke." (PMID 41249771, 2025).
Liver abscess (1 paper, 2025). A circumscribed area of pus or necrotic debris in the liver. "While the direct link between CYP7A1 expression and liver abscess formation in cattle has not been established, lower cholesterol circulation levels have already been reported to be linked to liver abscesses in cattle." (PMID 40489480, 2025).
liver inflammation (1 paper, 2021). "Previous studies have shown that Cyp7a1 is positively associated with liver inflammation." (PMID 33777984, 2021).
malnutrition (1 paper, 2022). Inadequate nutrition resulting from poor diet, malabsorption, or abnormal nutrient distribution. "Limited data from pre-clinical models of malnutrition and malnourished children suggest that the increased levels in bile acids lead to FXR activation and an increase in FGF-19 subsequently leading to suppressed hepatic bile acid synthesis, illustrated by decreased Cyp7a1 expression." (PMID 36402829, 2022).
melanoma (1 paper, 2022). A malignant, usually aggressive tumor composed of atypical, neoplastic melanocytes. "Hence, administration of bile acids, generated from cholesterol in a CYP7A1 manner, promotes the growth of lymph node-metastatic melanoma, while depletion of CYP7A1 has an opposite effect." (PMID 35945203, 2022).
morbid obesity (1 paper, 2015). An excess of body weight, normally defined as an individual with a body mass index greater than 35 or a body weight greater than one hundred percent of ideal body weight. "We found that highly enriched UDCA enhances de novo BA and cholesterol synthesis via induction of several BA and cholesterol synthetic markers and enzymes such as C4, 7α-hydroxycholesterol and CYP7A1 (for BAs) and hepatic SREBP2 and HMGCR (for cholesterol) in morbid obesity." (PMID 25617503, 2015).
Nephropathy (1 paper, 2022). A nonspecific term referring to disease or damage of the kidneys. "The enhanced cholesterol clearance in the circulation in mice with adenine-induced nephropathy can also be explained by the increase of Cyp7a1." (PMID 36009040, 2022).
infection (13 papers, 2009 to 2025). The state of being infected such as from the introduction of a foreign agent such as serum, vaccine, antigenic substance or organism. "Infection with lentiviruses expressing Prox1-targeting siRNA precursors si258 (lenti-si258) or si1646 (lenti-si1646) nearly obliterated endogenous Prox1 expression (top, lanes 1–3), and caused a marked increase in CYP7A1 mRNA level (bottom, bars 1–3)." (PMID 23626788, 2013). "Upon infection of CYP7A1 knockdown cells, we observed that the proliferation of STM ΔyqhD was similar to that of STM WT." (PMID 41036841, 2025). "On the other hand, infection by lenti-Prox1m resulted in overexpression of Prox1 (top, lane 4) and decrease in CYP7A1 mRNA level (bottom, bar 4)." (PMID 23626788, 2013). "The mRNA and protein levels of CYP7A1, the rate-limiting enzyme in the neutral pathway of bile acids synthesis, were decreased by infection." (PMID 24165751, 2013). "We thus determined whether infection with the S. Typhimurium wild type decreased expression of genes involved in bile acid synthesis, including Cyp7a1, Cyp8b1, Cyp27a1, and Cyp7b1." (PMID 40938708, 2025). "Interestingly, we also observed a two-fold increase in expression of CYP7A1 at 4 days post-infection." (PMID 30024933, 2018). "Remarkably, the mRNA and protein levels of CYP7A1, the rate-limiting enzyme in the neutral pathway of bile acids synthesis were decreased during infection, in spite of the lower levels of FGF15 which would be expected to promote the upregulation of Cyp7a1 expression." (PMID 24165751, 2013). "Vaccination has a complex influence on infection-induced changes in expression of hepatic nuclear receptors (CAR, FXR, RXR, and PXR) and of the metabolic enzymes Sult2a and Cyp7a1." (PMID 19341445, 2009). "Also, vaccination affects the infection-induced metabolic response with respect to SULT2A1 and CYP7A1, respectively." (PMID 19341445, 2009). "The upregulation of CH25H and downregulation of CYP7A1 in the current study suggest that pathogen infection may not only affect the BA metabolism, but also cholesterol metabolism, which needs to be further confirmed." (PMID 39287458, 2024). "Interestingly, the mRNA and protein levels of CYP7A1, were not altered in the liver of mice after either Ad-378 infection or Ant-378 treatment." (PMID 33754066, 2021).
metabolic disorders (11 papers, 2006 to 2026). "miR-33a is involved in the regulation of metabolic disorders, and specifically inhibits CYP7A1 mRNA." (PMID 32807146, 2020). "some studies suggest that pro-inflammatory cytokines IL-1β and TNF-α suppress the expression of CYP7A1 and NTCP, leading to decreased BA synthesis and a reduction in the hepatic-enterohepatic circulation rate, thereby contributing to BA metabolic disorders." (PMID 41255527, 2025). "Based on the results of transcriptomics, we further verified that LG attenuates NAFLD by restoring the metabolic disorder of BAs via the up-regulation of Fgf15/FXR in the ileum and down-regulation of CYP7A1/FXR in the liver." (PMID 38647315, 2024). "However, total BAs, and Abcc3, Abcc11, Cyp7a1 mRNA levels were unchanged in this study, suggesting that there might be a dynamic equilibrium of total BAs in GUDCA-alleviated diet-induced metabolic disorders." (PMID 34236076, 2021).
tumor (10 papers, 2018 to 2025). "Here, we provide evidence for the utility of our model by showing that cyp7a1-mediated tumor–liver interaction underlies altered neutrophil dynamics in the livers of tumor-bearing zebrafish larvae." (PMID 29592890, 2018). "In addition to tumor-induced systemic inflammation and hepatomegaly, hepatic expression of cyp7a1, the gene encoding the rate-limiting enzyme for synthesizing bile acids/alcohol, tended to be decreased at as early as 5-7 dpf in tumor-bearing larvae." (PMID 29592890, 2018). "Inhibition of taurine transporter abrogated the tumor-promoting effects of the bile acid synthesis enzymes CYP7A1 and BAAT." (PMID 41590614, 2025). "Down-regulated genes contain markers enriched in mature hepatocytes (Tat, Cyp7a1, Apoa5, Pck1, Cyp3a11, Mup3 or Acsl1) and tumor suppressors (Lect2, Wfdc17 or Efemp1)." (PMID 32372053, 2020). "Overexpression of cyp7a1 in the liver by means of the fabp10a promoter significantly restored total BA levels in tumor-bearing larvae." (PMID 29592890, 2018). "Overexpression of cyp7a1 in the liver significantly restored total BA levels both at 7 and 9 dpf in tumor-bearing larvae." (PMID 29592890, 2018). "Three major questions remain to be solved: which tumor-derived factor(s) alters cyp7a1-mediated cholesterol–BA flux and liver inflammation?" (PMID 29592890, 2018). "Second, using the model, we discovered a tumor–liver interaction that mediates enhanced recruitment of neutrophils to the liver in tumor-bearing larvae via a cholesterol-metabolizing gene, cyp7a1, as a critical host gene." (PMID 29592890, 2018). "We emphasize that our findings are of significance in that we redefined cyp7a1 as a host gene critical for mediating the tumor–liver–neutrophil crosstalk in vivo." (PMID 29592890, 2018). "Notably, CYP7A1+ hepatocytes were found to be in a transitional state of precancerous lesions, exhibiting characteristics of tumour cells and inflammation." (PMID 37994257, 2024). "Consistent with the FGF19/FGFR4 downstream pathway, tumor PD assessed by RNAseq revealed an upregulation of CYP7A1 transcript concomitant with downregulation of the MAPK target gene DUSP6, in most on-treatment biopsies obtained at C1D8 with respect to the matched pretreatment sample." (PMID 35655320, 2022). "In addition, increased CYP7A1 expression and bile acid synthesis ameliorated hepatic inflammation and fibrosis, proving its anti-tumor effects." (PMID 34777484, 2021). "On the basis of these, we found that a tumor–liver crosstalk, which can be defined by expression of hepatic cyp7a1 accompanied by altered cholesterol–bile alcohol (BA) flux, promote infiltration of neutrophils to the liver (liver inflammation) in tumor-bearing larvae." (PMID 29592890, 2018). "In order to investigate whether the altered cyp7a1 expression in the liver affects tumor-induced systemic phenotypes, we generated a transgenic line expressing cyp7a1 under the control of the fabp10a promoter." (PMID 29592890, 2018). "Western blot (WB) experiments revealed that the expression level of CYP7A1 starts increasing at the stage of NASH, continues to rise until the onset of tumours, and subsequently declines during the tumour stage." (PMID 37994257, 2024). "We found that CYP7A1, GINS2, and PDLIM3 were significantly up-regulated, and MYC, MAMDC4, ADAMTS1, THBS1, and RASD1 were significantly down-regulated in HCC tumor samples compared to normal samples." (PMID 34777484, 2021). "We found that CYP7A1, GINS2, and PDLIM3 were significantly up-regulated, and MYC, MAMDC4, ADAMTS1, THBS1, and RASD1 were significantly down-regulated in HCC tumor samples compared with normal samples using the TCGA dataset." (PMID 34777484, 2021). "The observed decrease is not due to an impaired bile acids synthesis by tumor cells, as the expression of the rate-limiting enzymes Cyp7a1 and Cyp27a1 was not affected in the transition from inflammation to tumors." (PMID 29734330, 2018).
tumor (continued). "An importance of hepatic cyp7a1 in the tumor's adverse effects on the host has not been previously appreciated." (PMID 29592890, 2018). "This indicated that cyp7a1 expression is the rate-limiting process for maintaining normal BA levels in tumor-bearing larvae." (PMID 29592890, 2018). "cyp7a1 has not been considered as a crucial host gene in tumor-induced distant inflammation." (PMID 29592890, 2018). "The expression of CYP7A1, ELOVL1 and ACACA were higher in LIHC tumor tissues than normal tissues." (PMID 38584256, 2024).